CAV1 (caveolin 1)
Diseases named in the same sentence as CAV1 in open-access papers (continued):
Sharing a sentence is not in itself a finding about the gene and the disease.
prostate carcinoma (continued). "Interestingly, Nabi and colleagues showed that CAV1 phosphorylation on tyrosine 14 stabilizes focal adhesion proteins and promotes cell motility in a CSD-dependent manner in prostate cancer cells." (PMID 32458269, 2020). "In comparing serum-free media with and without lipids, lipid-deprivation reduced Cav-1 protein expression in RM-9 and PC-3M prostate cancer cell lines." (PMID 32855410, 2020). "As indicated by the negative RNA expression value, caveolin-1 was downregulated in African American prostate cancer specimens compared to African American non-malignant control specimens; on the contrary, beta-catenin was upregulated." (PMID 28697756, 2017). "After subtracting race-specific non-malignant RNA expression, beta-catenin and caveolin-1 mRNA expression levels were higher in African-American prostate cancer specimens than in Caucasian-American specimens." (PMID 28697756, 2017). "After subtracting race-specific non-malignant RNA expression, caveolin-1 mRNA expression was higher in African-American prostate cancer patient specimens than in specimens from Caucasian-American patients." (PMID 28697756, 2017). "CAV1 and FASN are coordinately regulated in melanoma and prostate cancers, implying that their concomitant expression may enhance tumourigenesis." (PMID 27852311, 2016). "While caveolin-1 microdomains (not caveolae) are aberrantly induced in advanced prostate cancer cells, caveolae is reduced in the stroma during prostate cancer progression." (PMID 25924234, 2015). "It has been suggested that in prostate cancer, the tumour-promoting roles of Cav-1 are due to a non-caveolar form of the protein." (PMID 26328273, 2015). "Our data suggest a contrast between the non-aggressive and the aggressive prostate cancer cell lines in the pattern of cholesterol efflux and cav-1 expression." (PMID 23934233, 2013). "To the contrary, we found no expression of cav-1 mRNA in the non-aggressive prostate cancer cell lines." (PMID 23934233, 2013). "Moreover, the annotated genes in the constructed network, such as APC, AXIN1, AKT2, CCND2, CAV1, TLE2 and TCF4, are essential regulatory components of these pathways in prostate cancer." (PMID 23782521, 2013). "Hence our data support caveolar-dependent and caveolar-independent localization of caveolin-1 and PTRF/cavin-1 at discrete locations during transmigration in two different cell models: NIH3T3 fibroblasts and metastastic prostate cancer cells (PC3)." (PMID 22912783, 2012). "This study used the prostate cancer cell line LNCaP, which was shown to contain Triton X-100-insoluble fractions, but not caveolin-1." (PMID 18949068, 2007). "The prostate cancer cell line PC3 expresses high levels of caveolin-1 but does not express PTRF." (PMID 39857963, 2025). "These claims were further substantiated by studies in Cav1-positive PC3 prostate cancer cells lacking cavin-1 and hence devoid of caveolae in which Cav1 siRNA knockdown, specifically eliminating scaffolds, reduces downstream Rho signaling, focal adhesion signaling and cell migration." (PMID 38526159, 2024). "Caveolin-1 (Cav-1), the main component of the cavaeolae plasma membrane, promotes cell cycle progression through the Ras-ERK pathway and was previously identified in cell line models as a marker in aggressive prostate cancer LEVs for discriminating LEVs from exosomes." (PMID 33801459, 2021). "Moreover, these authors evaluated the biological effects of the conditioned media obtained from CAV1-expressing and secreting prostate cancer cells (LNCaP-CAV1) on recipient LNCaP cells lacking CAV1." (PMID 32458269, 2020). "Thus, increased expression and secretion of TRIAP1 by CAV1-silenced fibroblasts suggests that secreted TRIAP1 and then internalized by neighbouring prostate cancer cells, might account for the induced radiation resistance of these cells." (PMID 30871022, 2019).
prostate carcinoma (continued). "Importantly alterations in stromal Cav1 levels did not include the tumor vasculature because independent of the tumor stages Cav1 was highly expressed in tumor endothelial cells, even in advanced prostate carcinomas." (PMID 28112237, 2017). "The increased protein level of beta-catenin and the reduction of caveolin-1 protein level in the tumorigenic RC-77 T/E cells mirrored the upregulation of beta-catenin mRNA and downregulation of caveolin-1 mRNA in African-American prostate cancer specimens compared to non-malignant controls." (PMID 28697756, 2017). "In the present study we have investigated whether Caveolin-1 expression in non-malignant and malignant prostate tissue is a potential prognostic marker for outcome in prostate cancer patients managed by watchful waiting." (PMID 27764093, 2016). "PC3 is a metastatic prostate cancer cell line that expresses abundant levels of tyrosine phosphorylated Cav1 (pCav1) but lacks cell surface caveolae due to the absence of polymerase 1 and transcript release factor (PTRF)/cavin-1, required together with Cav1 for caveolae formation." (PMID 25942420, 2015). "However, ECs in tumor vessels did not exhibit an altered Cav1 expression during prostate cancer progression: a high expression of Cav1 was detected in the tumor vasculature in all tissue samples analyzed independently from the Gleason score." (PMID 25985209, 2015). "Firstly, caveolin-1 may function pathologically outside caveolae via non-caveolar caveolin-1 membrane raft domain (caveolin-1 microdomains), as discovered in PC-3 cells and validated in prostate cancer tissue samples." (PMID 25924234, 2015). "In normal prostate tissue, CAV1 has not been detected, but expression increases upon tumour formation in mouse models and human patients 24–27, and CAV1 presence promotes metastasis of prostate cancer cells through an autocrine/paracrine mechanism 23,28." (PMID 24500501, 2014). "Interestingly, human prostate cancer cells secreting caveolin-1 induced tumor growth of caveolin-1 negative tumor cells in vivo through the release of caveolin-1 associated to lipoprotein particles." (PMID 19381331, 2009). "In normal prostate tissue caveolin-1 is absent, but expression increases upon tumour formation in mouse models and human patients and caveolin-1 presence promotes tumour growth and metastasis of prostate cancer cells via an autocrine/paracrine mechanism." (PMID 18400052, 2008). "Our results also showed that caveolin-1 protein level was lower in malignant RC-77 T/E cells than non-malignant RC-77 N/E cells and that its mRNA expression was downregulated in African-American prostate cancer patient specimen compared to non-malignant African-American prostate specimen." (PMID 28697756, 2017). "Therefore, in prostate cancer, caveolin-1 is overexpressed without PTRF." (PMID 24123650, 2013). "Cav1 is an autocrine/paracrine factor that is up-regulated in metastatic PCa, CRPC and androgen insensitive prostate cancer, but not in hormone sensitive prostate cancer." (PMID 37910338, 2023). "To test the effects of Rosuvastatin treatment on the outcome of prostate cancer, we monitored the levels of PSA, CAV1 and EGFR at baseline, after 3 and 6 months in statin and non-statin users PC patients." (PMID 36480560, 2022). "The prostate cancer PC3 cell line was used, which expresses CAV1 but does not express any members of the Cavin family so that CAV1 is diffusely localised at the plasma membrane." (PMID 33568658, 2021). "The absence of interstitial caveolin-1 expression is related to the activation of AKT, which leads to the upregulation of TGF-β1 and SNCG expression and results in the transfer of prostate cancer cells." (PMID 30424755, 2018). "Taken together, our data show that hypercholesterolemia promotes prostate cancer metastasis independent of the androgen pathway, in part by increasing IQGAP1 and caveolin-1." (PMID 25924234, 2015).
prostate carcinoma (continued). "This is consistent with our studies showing that BODIPY-cholesterol-accumulating and aggressive prostate cancer cell lines overexpress cav-1 mRNA, whereas BODIPY-cholesterol poor and non-aggressive prostate cancer cell lines express low or no cav-1 mRNA." (PMID 23934233, 2013). "We manipulated the expression of PTRF in three prostate cancer cell lines, namely PC3 cells (which express abundant Cav-1 but no PTRF), LNCaP (which produce neither Cav-1 nor PTRF) and DU145 (which express both Cav-1 and PTRF)." (PMID 24123650, 2013). "Here we found the Cav-1 mediated increases in VEGF-A secretion to be independent of PI3-K/AKT and mTOR signalling, whereas Cav-1 appears to promote both the production and release of VEGF-A in prostate cancer cells at least in part through the potentiation of PI3-K/AKT signalling." (PMID 24119769, 2013).
lung carcinoma (121 papers, 2002 to 2026). "CRISPR/Cas9 technology has been proven to be capable of the specific gene alterations associated with treatment resistance with lung cancer caveolin-1 (CAV-1)." (PMID 39281673, 2024). "As reviewed elsewhere, Cav1 has also been implicated in multiple stages of lung cancer development, including cell proliferation, migration, apoptosis and drug resistance." (PMID 37696458, 2023). "In the family members of caveolins, CAV1, a main component of caveolae, exhibited anti-tumor functions in lung cancers, which was associated with cell proliferation, migration, apoptosis and drug resistance of lung cancer." (PMID 37497407, 2023). "In particular, Cav-1 is associated with lung cancer cell migration, invasion, and anoikis resistance." (PMID 33920031, 2021). "Specifically, out of 24 lung cancer patients, majority of cancer them had CAV-1 gene amplification linked with increased expression and copy number variation with significant p values." (PMID 34762666, 2021). "We also analyzed TCGA PanCan lung cancer patient’s data using cBioPortal and investigated role of CAV-1 mutation in clinical outcomes." (PMID 34762666, 2021). "High Cav-1 expression was also associated with a more aggressive behavior in melanoma cells and significantly shorter survival in lung cancer patients." (PMID 34590611, 2021). "As with many other cancers, overexpression of CAV-1 protein is associated with aggressiveness and metastasis, as well as poor clinical prognosis, in human lung cancer." (PMID 32733649, 2020). "In lung cancer, overexpression of CAV-1 protein is known to be associated with aggressiveness and metastasis, as well as poor clinical prognosis." (PMID 32733649, 2020). "The abnormal expression of Cav-1 detected in lung cancer has been closely linked to cancer progression such as cell proliferation, migration, apoptosis and drug resistance." (PMID 31991790, 2020). "In 293 pairs of lung cancer tissues and their adjacent normal tissues, Cav-1 is also found to be associated with smoking (P = 0.011)." (PMID 31901898, 2020). "A high Cav-1 level has been shown to be associated with drug resistance during the treatment process of numerous cancers such as lung cancer, esophageal cancer, colorectal cancer and renal carcinoma." (PMID 31991790, 2020). "In our study, the expressional pattern of CAV1 in the primary tumor-associated stroma was analyzable for 147 primary lung cancer cases." (PMID 29850392, 2018). "Loss of caveolin-1 expression was observed in several studies concerning lung cancer, thus supporting our insight into the mechanisms of the relationships observed in our study." (PMID 30235348, 2018). "We conducted a study to explore the relationship between CAV1 gene polymorphism, expression level and lung cancer." (PMID 29190968, 2017). "Cav-1 was shown to associate with metastatic potentials of lung cancer cells, while its role on cancer cell adhesion is still unclear." (PMID 23460862, 2013). "Cav-1 has been reported to promote tumor cell migration and invasion, and an increase in Cav-1 expression is associated with tumor metastasis in lung cancer." (PMID 23984323, 2013). "For example, loss of caveolin 1 expression and overexpression of cyclin B1 in lung cancer tissue have previously been reported in studies with cDNA arrays and immunohistochemical analyses." (PMID 22348039, 2012). "Recent research implicated caveolae and Cav1 in pathogenesis of human lung disease, neurodegenerative diseases, and lung cancer." (PMID 22506115, 2012). "Indeed, cancer metastasis and patients’ poor prognosis have been associated with CAV1 downregulation in ovarian, breast, and lung carcinomas and with CAV1 upregulation in bladder or nasopharyngeal carcinoma." (PMID 39201614, 2024).
lung carcinoma (continued). "Also, TCGA PanCancer clinical studies have demonstrated amplification, deletions and missense mutation in CAV-1 gene in lung cancer patients, and that CAV-1 alteration has been linked to poor prognosis, and poor survival in lung cancer patients." (PMID 34762666, 2021). "Our present investigation on the role of CAV-1 in radio-resistance, and important clinical findings based on cancer genome data suggest that CAV-1 gain of function mutation might be a driver mutation in lung cancer tumor aggression." (PMID 34762666, 2021). "In recent report CAV-1 has been linked to radiation and chemoresistance in cisplatin-resistant ovarian cancer cells, Thus, based on our data we concluded that overexpression of caveolin-1 contributes to radio-resistance and tumor aggression in lung cancer." (PMID 34762666, 2021). "Epigenetic modification of Cav-1 is proved to be associated with lung cancer development." (PMID 31901898, 2020). "In conclusion, the results indicated that rs1049337, it's a SNP located at 3′UTR region of CAV1 may affect lung cancer risk by altering the binding affinity between the mRNA of CAV1 and the corresponding microRNAs." (PMID 29190968, 2017). "In our study, rs959173-C allele was a protective allele for NSCLC risk and the expression of CAV1 was down regulated in lung cancer tissue, which suggested us that rs959173 is likely to participate in the onset and development of NSCLC by affecting the expression of CAV1." (PMID 28148898, 2017). "Caveolin-1 (Cav-1) is a multifunctional scaffolding protein that is associated with directional cell migration and lung cancer invasion; however, its precise role in lung cancer electrotaxis is unknown." (PMID 29221162, 2017). "On the other hand, caveolin-1 expression was elevated in carcinoma of the thyroid, associated with tumor dedifferentiation in bladder cancer, and enhanced the invasive capability of lung cancer cells lines." (PMID 25756273, 2015). "In addition, the expression level of Cav-1 was shown to be associated with a poor prognosis and metastasis in several cancers, including prostate, pancreas, and lung cancers." (PMID 24955034, 2014). "Since an upregulation of NO, as well as Cav-1 protein, is associated with an aggressive status in lung cancer cells, therefore the results from this study may lead to a better understanding of lung cancer pathology." (PMID 23984323, 2013). "Likewise, elevated Cav-1 expression was associated with an increased metastasis capacity and poor survival in lung cancer patients." (PMID 23984323, 2013). "RESULTS: Eight PANoptosis-related genes (DAPK2, CAV1, PDK4, IL3RA, NOTCH1, CHMP4B, IRAK1, and SFN) were identified as being significantly associated with lung cancer." (PMID 41760846, 2026). "Cav-1 and autophagy are also involved in the process of chemotherapy and radiotherapy in lung cancer." (PMID 41030451, 2025). "Studies indicate that Cav1 inhibition reduces EV uptake in various cell lines, including lung cancer cells." (PMID 40963741, 2025). "Cav1 is often downregulated or lost in breast, colon, ovarian, and lung cancers, suggesting a tumor-suppressive function." (PMID 40963741, 2025). "CAV1 knockdown enhances the therapeutic sensitivity of lung cancer to cisplatin-induced apoptosis by inhibiting parkin-related mitophagy and activating ROCK1 pathway." (PMID 40303344, 2025). "In detail, according to the different types of lung cancer, CAV1, CAV2, CAVIN1 and CAVIN2 had a dramatically lower expression in lung adenocarcinoma, squamous cell lung carcinoma and large cell lung carcinoma." (PMID 37497407, 2023). "It has been shown that caveolin-1 levels are significantly downregulated in A549 lung cancer cells after cisplatin exposure." (PMID 37215569, 2023). "Mice lacking caveolin-1 and caveolin-2 have severe lung abnormalities, and abnormal caveolin-1/2 expression is involved in idiopathic pulmonary fibrosis, lung cancer, and pulmonary hypertension." (PMID 37759535, 2023).